RIPK3 (receptor interacting serine/threonine kinase 3)
Diseases named in the same sentence as RIPK3 in open-access papers (continued):
Sharing a sentence is not in itself a finding about the gene and the disease.
tumor (continued). "RIPK3 ubiquitination is enhanced with the phospho-mimetic S9D parkin, providing evidence that parkin phosphorylation at S9 has a protective, tumor suppressor effect against necroptosis and tumor formation." (PMID 35327659, 2022). "It is possible that RIPK3 regulates anti-tumor immunity via a necroptosis-independent pathway." (PMID 36077828, 2022). "Through the use of CC models, PolyIC-driven immunogenicity has been shown to be dependent on the necroptosis regulator RIPK3 in tumor cells, suggesting that RIPK3 could serve as a novel predictive marker for the personalization of cancer immunotherapy." (PMID 36685937, 2022). "The four genes have been found to influence tumor progression in HNSCC via necroptosis regulation; Poly (ADP-ribose) polymerase-1 (PARP1), as a chromatin-associated enzyme in DNA repair; and a downstream effector of RIPK1/RIPK3 pathway in necroptosis." (PMID 36349193, 2022). "In addition, Ripk3‐null mice develop increased thymic tumor formation accompanied by reduced host survival in the context of an N‐ethyl‐N‐nitrosourea (ENU)‐induced tumor model." (PMID 36161785, 2022). "Another key protein RIPK3 plays a critical role in tumor suppression." (PMID 35884370, 2022). "Our study thus provides the evidence demonstrating the tumor suppressive function of RIPK3 and suggests that the measurement of RIPK3 levels may be clinically relevant for tumor prognosis and therapy." (PMID 36161785, 2022). "RIPK3 expression is often silenced in various cancer cells, which suggests that it may have tumor suppressor properties." (PMID 36161785, 2022). "Specifically, it has been shown that in pancreatic ductal adenocarcinoma (PDA), when RIPK3 knockout tumor cells undergo necroptosis, soluble cytokines released bind to receptors on inflammatory cells, triggering an immunosuppressive tumor microenvironment and promoting the progression of PDA." (PMID 36357839, 2022). "However, blocking IL-6 signals by anti-IL-6R antibody therapy was sufficient to suppress tumor formation in anti-IL6-R-treated Apcmin/+Ripk3-/- mice." (PMID 33996591, 2021). "However, that of MLKL in both hilar and intrahepatic CCA was much lower than that of RIPK3 in adjacent tumor tissues, in which 88.7% of the patients had a median H-score of 22.03, which was subsequently interpreted as negative." (PMID 34083572, 2021). "Additionally, the immunohistochemistry assay identified the upregulation of caspase-4, GSDMD, and phospho-RIPK3 expression in xenograft tumor tissues following NO.0449-0145 treatment." (PMID 34006852, 2021). "Future investigation will be needed to determine how these proteins regulate Ripk3 expression in ECs and whether they impact RIPK3 function in the context of developmental and tumor angiogenesis." (PMID 34153072, 2021). "We next examined the levels of RIPK3 in different stages of CRC tumor progression." (PMID 33996591, 2021). "Thus, RIPK3 activation-dependent regulation of TRIM28 in cancer cells is likely to significantly contribute to a robust cytotoxic anti-tumor immunity." (PMID 34419074, 2021). "We hypothesized that RIPK3 deletion might increase the tumor burden in Apcmin/+ mice during intestinal tumorigenesis." (PMID 33996591, 2021). "Tumour necroptosis is regulated by RIPK3 during tumour development." (PMID 33976222, 2021). "Downregulated expression of RIPK3 is correlated with poor prognosis in multiple tumor types." (PMID 33996591, 2021). "Furthermore, necroptosis-associated effector proteins RIPK1, RIPK3 and MLKL, identified in the Clinical Proteomic Tumor Analysis Consortium (CPTAC) validation cohort, were all up-regulated in the tumors, in line with our transcriptomic findings." (PMID 33672863, 2021). "RIPK3 depletion could generate an immunosuppressive tumor microenvironment and tumorigenesis in pancreatic adenocarcinoma (PDA) experimental mouse model." (PMID 34083572, 2021). "Tumor progression in Apcmin/+Ripk3-/- mice and those of Apcmin/+ mice was analyzed." (PMID 33996591, 2021).
tumor (continued). "Moreover, Apcmin/+Ripk3-/- mice exhibited increased tumor numbers and tumor loads compared with in Apcmin/+ mice." (PMID 33996591, 2021). "In the anti-tumor immune response, RIPK3 also has a pivotal role." (PMID 33567618, 2021). "We further evaluated the role of TNF/RIPK3 in the fate of KC post PH in tumor-inoculated mice." (PMID 33178579, 2020). "DNA hypomethylating agents can restore RIPK3 expression in cancer cells, “rescuing” their necroptotic capacities and enhancing various beneficial effects of chemotherapy, including promotion of anti-tumor immunity." (PMID 32752206, 2020). "Therefore, the immunocompetent BALB/c mice injected with necroptotic DD_RIPK3 cells showed effective anti-tumor responses." (PMID 32764483, 2020). "Moreover, in combination with anti-PD1 treatment, AAV vector-mediated intratumoral RIPK3 expression resulted in further improved tumor rejection and overall mice survival." (PMID 32674264, 2020). "In addition, RIPK3 can be induced or upregulated in vivo under certain conditions, e.g., upon tumor cell injection." (PMID 32332696, 2020). "Mechanistically, this was linked to an increased RIPK1/RIPK3-dependent protein product of PDA cells (SAP130), which promoted cellular immune suppression by tumour infiltrating macrophages expressing the protein receptor (Mincle) that were themselves recruited in a CXCL1-dependent manner." (PMID 31416294, 2019). "However, somewhat counterintuitively, the expression of RIPK1 and RIPK3 was tumour promoting in this case." (PMID 31416294, 2019). "Our in vivo results and published tumor xenograft experiments using immunocompromised animals show that the adaptive immune response (e.g., T cells) is not necessary for the loss of RIPK3 expression in tumor cells." (PMID 30157175, 2018). "Therefore, one needs to consider the potentially negative consequences of reactivating necroptosis by inducing the lost RIPK3 expression, because increase in necroptosis and inflammation can fuel tumor growth." (PMID 30157175, 2018). "Interestingly, our tumor xenograft studies, as well as transcriptomics analyses of published RNAseq/microarray datasets of patient tumor biopsy samples, show that RIPK3 expression is lost progressively during tumorigenesis." (PMID 30157175, 2018). "This suggested the loss of RIPK3 in the tumor microenvironment did not affect established tumor cells from growing." (PMID 28151480, 2017). "Finally, to assess if necroptosis was indeed the reason for the decrease in tumor nodules in the lung, we injected B16-F10 cells tail vein into wild-type, Mlkl−/− and Ripk3−/− mice." (PMID 28151480, 2017). "In addition, changes in cytokine production in Ripk3−/− mice compared with wild-type mice after tumor injection were minimal." (PMID 28151480, 2017). "The overall percentage of dead wild-type ECs (either early apoptotic or late apoptotic/necrotic cells) increased by 1–3% with the increasing amount of tumor cells, whereas Ripk3−/− or Mlkl−/− ECs only showed an increase in 1–2% dead cells upon 9 × 104 tumor cell addition." (PMID 28151480, 2017). "The size of the tumor nodules was categorized into large, medium or small based on width of the nodule from pictures of the lungs and although not significant, there was a tendency toward smaller nodules in Ripk3−/− mice." (PMID 28151480, 2017). "Further investigation of other permeability factors in vivo and whether these ligands can form complexes of RIPK1/RIPK3 will be of interest to determine if these intracellular proteins can be targeted to block several pathways involved in tumor metastasis." (PMID 28151480, 2017). "This suggested RIPK3 may have an additional role to that of the proposed tumor cell induced necroptosis as proposed." (PMID 28151480, 2017). "Yet, the implication of RIPK3 in the pathogenesis of CRC in more physiological settings remains unclear and whether RIPK3-dependent necroptosis has tumor suppressive functions needs to be uncovered." (PMID 27344176, 2016).
tumor (continued). "Clearly, the drug-sensitizing effect of RFC11 in cancer cells is noticeable which is reflected in its synergistic anticancer effect and for its very prominent simultaneous upregulation of RIPK1 and RIPK3 expressions, as are evident in cellular and tumor levels." (PMID 27556106, 2016). "Similar to CRC patients, we found that RIPK3 mRNA was highly reduced in IBD-associated tumor tissues relative to adjacent non-tumoral tissues." (PMID 27344176, 2016). "Pointing to factors independent from RIPK3 that additionally regulate the resistance of tumor cells against programmed necrosis, MKN-28 cells expressed similar levels of RIPK3 as Colo357 or Panc89 cells but were resistant to both TRAIL/zVAD/CHX and TNF/zVAD/CHX." (PMID 24507727, 2014). "In a complementing experiment, we found that downregulation of RIPK3 by RNA interference in U-937 and HT-29 cells as two sensitive tumor cell lines that express relatively high levels of RIPK3 significantly blocked TRAIL/zVAD/CHX- as well as TNF/zVAD/CHX-induced necrotic killing." (PMID 24507727, 2014). "Susceptibility/resistance of the investigated tumor cell lines to programmed necrosis seems to primarily depend on expression of the pro-necrotic kinase RIPK3 rather than the related kinase RIPK1 or cell surface expression of TRAIL receptors." (PMID 24507727, 2014). "Identification of the mechanism by which RIPK3 regulates cisplatin-induced programmed necrosis may help predict the tumor's response to chemotherapy and radiotherapy." (PMID 24959694, 2014). "Overall, this set of experiments shows that apoptotic drug-tolerant persisters bear molecular features of vulnerability to necroptosis (increased RIPK3 expression and reduced C8 activity), that could possibly be used to effectively kill resistant tumor cells to repeated treatments." (PMID 41034453, 2025). "Notably, the effects of GADD45β are in line with emerging models of sublethal necroptosis, in which partial activation of RIPK3 promotes sustained NF-κB signaling, whereas its complete activation toward full necroptosis leading to a more immunogenic tumor environment." (PMID 41354733, 2025). "In addition, RIPK3 is also one of the key molecules regulating tumor immunity." (PMID 38461272, 2024). "In constructed mouse models, RIPK1/RIPK3 has the ability to enhance the expression of sin3A‐associated protein 130 (SAP130), CXCL1 and CXCL5, leading to the phenomenon that macrophages polarize towards M2 direction while promoting immunosuppression and tumour metastasis mediated by M2‐type cells." (PMID 38652105, 2024). "In addition, RIPK3 participates in the pathological process of several infections, aseptic inflammatory diseases, and tumors (including tumor-promoting and -suppressive activities) by regulating autophagy, cell proliferation, and the metabolism and production of chemokines/cytokines." (PMID 38684668, 2024). "Furthermore, low expression of RIPK3 suggests a poorer prognosis for tumor patients." (PMID 37351504, 2023). "Here, we utilized a system to drive RIPK3-dependent necroptosis or apoptosis without strong death-independent cytokine expression to interrogate the impact of necroptosis-associated DAMPs release in tumor immunity." (PMID 38196632, 2023). "As tumor cells undergoing necroptosis may release soluble factors favoring peri-tumoral immune suppression that two cytokines, CXCL1 and SAP130, were identified to be downregulated in RIPK3-deficient pancreatic ductal adenocarcinoma." (PMID 36849530, 2023). "Thus, revisiting the unidentified role of RIPK3 as a tumor suppressor could lead to new therapeutic modalities targeting cancer patients." (PMID 36161785, 2022). "In addition, high NRGscore patients always had more mRNA levels of three necroptosis-driving genes (MLKL, RIPK1, and RIPK3), further validating that necroptosis could play a tumor-promoting role in HCC." (PMID 35875102, 2022).
tumor (continued). "Intra-tumoral necroptosis not only promoted tumor antigen loading through tumor antigen presenting cells based on RIPK1/ RIPK3 ectopic activation, but also enhanced DC-, and CD8 + T cell-mediated anti-tumor immunity function, which might provide a new idea for current T-cell-based immunotherapy." (PMID 36175606, 2022). "Thus we speculate that Ripk3 mediates a Tnf-α-stimulated tumor-repressing activity through induction of protein synthesis and cellular senescence in HSCs." (PMID 35561683, 2022). "The mRNA level of RIPK3 might be a biomarker in tumor progression." (PMID 35957699, 2022). "RIPK3 deficiency did not alter nevi expansion or tumor growth in either sex." (PMID 35422482, 2022). "Hence, the expression of TNFR1 and of RIPK1/RIPK3/MLKL proteins by tumor cells, in conjunction with the production of TNFα in the tumor microenvironment, could represent novel biomarkers for cisplatin sensitivity in apoptosis-resistant tumors." (PMID 34490126, 2021). "For instance, while multiple studies have indeed found that, whole tumor-biopsy level, high expression of RIPK3 or even sometimes MLKL may predict prolonged cancer patient survival, yet high expression of RIPK1 or MLKL has also been documented to predict worse prognosis for some cancer patients." (PMID 32752206, 2020). "The tumor-suppressing activity of necroptosis has been shown in many types of cancer in which the expression of RIPK3 or MLKL is silenced by methylation or altered by polymorphisms in coding genes, suggesting that cancer cells evading apoptosis may also escape from necroptosis." (PMID 33050394, 2020). "In fact, absence of RIPK3 in cancer cells is documented to reduce the type I IFNs-mediated immune responses following treatment with chemotherapy; such that, failure to induce necroptosis (due to lack of RIPK3 or MLKL) can hamper tumor-associated immune infiltration after chemotherapy." (PMID 32752206, 2020). "Moreover, some chemokines released from necroptotic cells can in fact support pro-cancerous processes, e.g., RIPK3/RIPK1-driven CXCL1 in pancreatic cancer can facilitate tumor progression (via TAMs and MDSCs) by restricting infiltration of highly immunogenic T or B cells." (PMID 32752206, 2020). "First, tumor bearing mice in which caspase 3/7 expression was ablated specifically in intestinal epithelial cells (IEC) (Casp3/7ΔIEC) failed to respond to OXA while RIPK3-deficient animals disabled for necroptosis of the IEC controlled tumor outgrowth during OXA therapy." (PMID 33381121, 2020). "The findings that RIPK3 expression is silenced in many types of tumor cell lines and cancers and that necroptosis augments the anti-tumor activity of T cells leads to the speculation that necroptosis inhibition may be a key event for tumor development in some types of cancers." (PMID 31922095, 2019). "However, whether RIPK1-dependent and RIPK3-independent necroptosis was induced in AdipoRon-administered MIAPaCa-2 tumours remains unknown." (PMID 30038429, 2018). "Thus, the cost/benefit for a tumor to lose RIPK3 expression could be dependent on the extent of necessity for the tumor cells to evade the immunity of the patient." (PMID 30157175, 2018). "Furthermore, while RIPK3-induced cytokine production and necroptosis-induced inflammation (or necroinflammation) can fuel the tumor cell growth, such RIPK3-dependent processes may also promote antitumor immunity and programmed cell death of the tumor cells." (PMID 30157175, 2018). "Interestingly, although the kinase activity of RIPK1 was required, it appeared the loss of kinase activity from RIPK3 was not required in tumor formation in the lung." (PMID 28151480, 2017). "This study also provides first evidence using a physiologically relevant in vivo model of CRC and raises the possibility that RIPK3-mediated responses might act to retard tumor growth in the intestine and that necroptosis might be tumor-suppressive in the intestine." (PMID 27344176, 2016).
tumor (continued). "Studies have shown that radiation therapy significantly upregulates the expression of MLKL in tumor cells and activates the RIPK1/RIPK3/MLKL axis through the ZBP1‐mediated pathway, directing tumor cells to undergo necroptosis." (PMID 41287826, 2025). "RIPK3 has been shown to induce cytokine secretion, activate NKT cells, and enhance their tumor-killing activity." (PMID 39949740, 2025). "Restoration of RIPK3 expression can reactivate the epigenetic modifications of MLKL and induce necroptosis, thereby suppressing tumor growth." (PMID 40900810, 2025). "For instance, MLKL-mediated necroptosis releases CXCL5, which recruits MDSCs and suppresses T-cell activity while elevated RIPK3 expression drives an immunosuppressive microenvironment through CXCL1, thereby accelerating tumor progression." (PMID 41267084, 2025). "We next evaluated protein expression profiles using data from the Clinical Proteomic Tumor Analysis Consortium, which confirmed elevated RIPK1, RIPK3, and MLKL protein abundance in GBM relative to normal tissue." (PMID 41429922, 2025). "Necroptosis, initiated by Receptor-Interacting Protein Kinase 1 (RIPK1)/RIPK3-MLKL signaling, leads to the release of High Mobility Group Box 1 (HMGB1) and supports cross-presentation of tumor antigens, thus linking cell death to immune surveillance." (PMID 41235238, 2025). "In contrast, RIPK1 degraders employ the ubiquitin-proteasome system to completely clear RIPK1, simultaneously ablating scaffold-mediated survival signals and relieving inhibition on the RIPK3-MLKL pathway, significantly enhancing anti-tumour immunity." (PMID 41334873, 2025). "The expression and functional status of critical molecules comprising the PANoptosome, including ZBP1, RIPK1, RIPK3, CASP8, and ASC, can have a bidirectional impact on tumor survival, immune recognition, or tumor cell death." (PMID 40422233, 2025). "To further validate the robustness and broad-spectrum applicability of the RIPK3 system and cancer cell–based therapy, we investigated another GBM tumor model, GL261." (PMID 39560995, 2024). "RIPK1and RIPK3 are able to directly promote the priming of CD8+T cells and anti-tumor immune response." (PMID 38184626, 2024). "Activation of receptor-interacting protein kinases (RIPK1, RIPK3) promotes upregulation of chemokines, facilitating the infiltration of CD8 T cells and thereby enhancing anti-tumor immunity." (PMID 38983866, 2024). "The necroptotic signaling pathway mediated by RIPK1, RIPK3, and MLKL regulates the function of TAMs, influencing tumor progression." (PMID 39575419, 2024). "A comprehensive search on PubMed revealed a growing number of articles investigating RIPK family genes, particularly RIPK1, RIPK2, RIPK3 and RIPK4, in the context of tumor research." (PMID 38164277, 2024). "In the study, we also found high infiltration of PMN-MDSCs in the tumor microenvironment, and the expression of FATP2 was significantly up-regulated in the tumor microenvironment, while the expression of RIPK3 was significantly down-regulated." (PMID 38461272, 2024). "In the context of cancer, increased expression of A ADAR1-p150 has been demonstrated to restrict the binding of ZBP1 and RIPK3, consequently suppressing ZBP1-mediated PANoptosis to facilitate tumor growth." (PMID 38553639, 2024). "Accordingly, inhibition of cholesterol synthesis via itraconazole-mediated suppression of the upstream RIPK3-protein kinase B (AKT)-mammalian target of rapamycin complex 1 (mTORC1) pathway enhanced MDSC immunosuppressive activity and increased tumour burden." (PMID 38464388, 2024). "To include further characteristics of the tumor suppressive effect of RIPK3, we investigated the proliferation/migration behavior of HEK cells after RIPK3 induction using a wound healing assay." (PMID 38397165, 2024). "Along with the anti-tumour immunity of RIPK1 and RIPK3, a recent study demonstrated that exogenous injection of necroptotic cells to the TME induces RIPK-mediated secretion of cytokines." (PMID 38698968, 2024).